EIF4E (eukaryotic translation initiation factor 4E)
Diseases named in the same sentence as EIF4E in open-access papers (continued):
Sharing a sentence is not in itself a finding about the gene and the disease.
tumor (continued). "EIF4E expression was significantly associated with tumor diameter (P = 0.036)." (PMID 25342548, 2014). "However, we did find that pre-treatment eIF4E activity in tumours was significantly associated with substantial changes in the expression of eIF4E and its regulators post-treatment." (PMID 21320304, 2011). "Moreover, the loss of eIF4E reduced primary tumor growth and the onset of pulmonary metastasis." (PMID 32759815, 2020). "Tumour cell growth in secretome of activated PSCs caused a significant increase in the expression of proteins of translation initiation, such as translation initiation factor eIF-2B subunit alpha (eIF2B-1) and particularly eukaryotic translation initiation factor 4E (eIF4E)." (PMID 30923340, 2019). "Indeed, eIF4E is considered to be a proto-oncogene and its overexpression causes tumorigenic transformation of fibroblasts, while the overexpression of Hsp27 causes the resistance of tumor cells to treatment." (PMID 29100389, 2017). "Although further validation may be necessary, these data suggest that high expression of eIF4E in tumor, together with traditional risk factors such as lymphonodus status and tumor staging, may serve as a biomarker for a metastatic phenotype and a prognostic factor for poor survival in human ESCC." (PMID 27588477, 2016). "As phosphorylation of eIF4E is associated with tumour cell formation and increased resistance of tumour cells to apoptosis, sumoylation of eIF4GI at this site could provide a novel and undiscovered mechanism to regulate cell growth and proliferation in mammalian cells." (PMID 24818994, 2014). "The pivotal role of eIF4E is underscored here as a key signaling mediator, facilitating the communication between tumor and immune cells via EVs to promote immune suppression and suggesting HMGCR as a potential therapeutic target for tumor immunotherapy." (PMID 40820860, 2025). "The administration of EVs obtained from cells that overexpressed eIF4E increased tumor weight, ascites volume, and body weight." (PMID 40820860, 2025). "Our data demonstrate that tumor‐derived EVs, through the action of eIF4E, impact the protein synthesis in macrophages, notably augmenting the translation of genes associated with cellular metabolism." (PMID 40820860, 2025). "Accumulating evidence has shown that the overexpression of eIF4E and its phosphorylated form is correlated positively with tumor burden and also leads to poor prognosis in NSCLC." (PMID 40308810, 2025). "eIF4E-independent translation is particularly important under stress conditions such as tumor hypoxia, viral infection, DNA damage, and nutrient deprivation." (PMID 41308988, 2025). "Among them, m7G acts through METTL1/WDR4 and eIF4E to shape translation and RNA processing across coding and non‐coding transcripts, yielding oncogenic or tumour‐suppressive outputs in a context‐dependent manner." (PMID 41208200, 2025). "Here, it is demonstrated that extracellular vesicle‐packaged eIF4E from tumor cells alters protein translation in macrophages, contributing to antitumor immune response." (PMID 40820860, 2025). "TEM images using immunogold staining for eIF4E and eIF4A1 confirmed the presence of these proteins within tumor cells derived EVs." (PMID 40820860, 2025). "We elucidated how eIF4E‐packaged EVs affect metabolic profiles in macrophages within the tumor microenvironment." (PMID 40820860, 2025).
tumor (continued). "Mechanistically, tumor derived EV‐packaged eIF4E significantly enhances the expression of 3‐hydroxy‐3‐methyl‐glutaryl‐coenzyme A reductase (HMGCR), driving the synthesis and secretion of cholesterol." (PMID 40820860, 2025). "In contrast, in poorly vascularized tumor areas, mTOR and eIF4E are inactive, while 4EBP1 is activated, which thus facilitates tumor cell survival and favors tumor growth in the long term." (PMID 40670359, 2025). "Our research sheds light on the mechanism whereby tumor cells exploit EVs to transport eIF4E, a critical translation‐regulating molecule, to macrophages, thereby dampening antitumor immune responses." (PMID 40820860, 2025). "Immunohistochemistry (IHC) and western blotting analysis also revealed a significant increase in eIF4E and Ki67 levels in tumor tissue after eIF4E overexpression and a significant decrease in eIF4E and Ki67 levels in the eIF4E KD group." (PMID 40820860, 2025). "Ribavirin, a broad‐spectrum antiviral compound, exerts its anti‐tumour effects by competing with eIF4E for binding to the m7G cap." (PMID 41208200, 2025). "More recently, EGPI-1, another small molecule blocking the eIF4E-eIF4G interaction, was identified and shown to exhibit anti-tumour activity in vitro and in vivo." (PMID 40805230, 2025). "Strikingly, we found that the EVs derived from tumor cells exhibit elevated levels of translation initiation factor eIF4E." (PMID 40820860, 2025). "These collective findings underscore the pivotal role of tumor derived EVs packed with eIF4E in reprogramming macrophage metabolism." (PMID 40820860, 2025). "This conclusion is supported by functional experiments showing that overexpression or knockdown of eIF4E in tumor cells leads to a corresponding increase or decrease in PD‐L1 expression in macrophages." (PMID 40820860, 2025). "The remaining (∼70%) cytosolic 4E-BP1 is pivotal in facilitating a switch from cap-dependent to eIF4E-independent mRNA translation under hypoxia, promoting tumor angiogenesis and growth." (PMID 41308988, 2025). "In summary, our study provides evidence that eIF4E‐loaded EVs derived from tumor cells induce translational reprogramming and increase the expression of HMGCR in macrophages." (PMID 40820860, 2025). "Tumor cells cocultured with eIF4E‐EV treated macrophages exhibited significantly elevated cholesterol levels when compared to both the no EV and control EV groups." (PMID 40820860, 2025). "It was shown to inhibit eIF4E phosphorylation, exhibiting anti-tumour properties both in vitro and in vivo." (PMID 40805230, 2025). "In the hypophosphorylated state, 4E-BP1 is active and binds eIF4E, with antiproliferative and tumor-suppressive effects." (PMID 39869680, 2025). "Since tumor cells are “addicted” to aberrant eIF4E-dependent protein synthesis, translational control serves as an “Achilles heel” that has emerged as a promising therapeutic target." (PMID 39869680, 2025). "Overall, our study uncovered an overlooked oncogenic mechanism involving eIF4E‐packaged EVs that upregulate cholesterol synthesis in macrophages, fostering immune suppression within the tumor microenvironment." (PMID 40820860, 2025). "Early preclinical findings indicated that ASO LY2275796 (also referred to as ISIS 183750) achieved on-target silencing of eIF4E mRNA in human tumour xenograft models, significantly suppressing tumour growth." (PMID 40805230, 2025). "In NSCLC, inhibition of BRD4 enhances tumor necrosis factor-related apoptosis-inducing ligand (TRAIL)-induced apoptosis and restrains tumor growth by downregulating eukaryotic translation initiation factor 4E (eIF4E)." (PMID 41184230, 2025). "According to one research, EIF4E3 depends on cap‐binding activity to operate as a tumour suppressor and compete with EIF4E's growth‐promoting capabilities." (PMID 38071502, 2024).
tumor (continued). "PHGDH also interacts with the translation initiation factors eIF4E and eIF4A1 to promote translation initiation in the cytoplasm, thereby accelerating tumour development." (PMID 38577610, 2024). "Our study indicates that 4EBP1/eIF4E is the major signaling that modulates tumor cell proliferation and metabolic pathways, such as PKM1 and LDHA/C, that directly contribute to tumor proliferation." (PMID 39325536, 2024). "Another study found that cinobufagin can inhibit the AURKA-mTOR-eukaryotic translation initiation factor 4E (EIF4E) signaling pathway, and block the formation of the spindle body in Huh-7 cells, thereby exerting an anti-tumor effect." (PMID 38803433, 2024). "Studies have suggested that the eIF4E subunit of the eIF4F complex enhances tumour growth and induces therapy resistance by increasing the translation of oncogene mRNAs." (PMID 39529201, 2024). "In HCC, RACK1 was found to promote tumor growth and chemoresistance through the promotion of eIF4E phosphorylation." (PMID 39199296, 2024). "As a primary downstream target of mTORC1 signaling, the 4EBP1/eIF4E cascade promotes c-MYC–driven HCC development by regulating tumor cell proliferation." (PMID 39325536, 2024). "Previous research has shown that Ribavirin would compete with EIF4E to join with m7G, hence limiting mRNA transcription and having a function in tumour therapy." (PMID 38071502, 2024). "4EGI-1 not only inhibited eIF4G1 binding but also stabilized 4E-BP binding, leading to enhanced inhibition of eIF4E activity, which is required for tumor suppression." (PMID 39409166, 2024). "EIF4E is often highly expressed in tumor cells, and few studies have investigated how the levels and activity of eIF4E are elevated in malignant cells." (PMID 37601696, 2023). "Specific ASOs targeting eIF4E can inhibit tumor growth by suppressing the translation of target mRNAs such as VEGF, Survivin, C-Myc, Cyclin D1, and BCL-2." (PMID 37631029, 2023). "The phosphorylation of eIF4E can stimulate the translation of tumor-promoting mRNAs, thus enhancing its carcinogenic characteristics." (PMID 37601696, 2023). "Among the major races represented in the database, Caucasian patients exhibited relatively higher levels of eIF4E expression in tumor tissues, followed by the African race." (PMID 37766871, 2023). "Probably the most promising drug target is phosphorylated eIF4E, its pivotal function in tumor progression having been described before." (PMID 36902316, 2023). "Specifically, ERK1/2 and p38MAPK can directly phosphorylate and activate MKNK1, promoting MKNK1‐mediated eIF4E phosphorylation, protein synthesis, tumour cell proliferation and metastasis." (PMID 37864471, 2023). "In tumor cells, eIF4E activity is abnormally increased, which stimulates cell growth, metastasis and translation of related proteins." (PMID 37601696, 2023). "The deregulation of protein synthesis downstream of mTORC1 at the level of 4E-BP1/eIF4E plays a central role in tumor formation, and 4E-BP1/eIF4E transfers the effect of oncogenic Akt signaling on mRNA translation, cell growth, and tumor progression." (PMID 37508495, 2023). "The 4E-BPs are negative regulators of eIF4E that are inactivated by mTORc1 phosphorylation; the knock-in of 4E-BP phosphomutants reduces the tumor burden." (PMID 36902316, 2023). "MNK activity and/or phosphorylation of eIF4E have been shown to be important for tumour initiation and/or progression and metastasis (e.g., 34)." (PMID 37143925, 2023). "Both these studies indicated that the availability of eIF4E and its control by mTORC1 are central to tumour development." (PMID 37143925, 2023).
tumor (continued). "The other downregulated miRNA found in our analysis, hsa-miR-455, targets eukaryotic translation initiation factor 4E (eIF4E), which affects the translation of selected mRNAs involved in the control of the tumor microenvironment and progression." (PMID 37372400, 2023). "The 4EBP-based therapeutic peptides hinder the progression of ovarian cancer by binding to eIF4E and disrupting tumor growth." (PMID 37631029, 2023). "The involvement of eIF4E and phosphorylated eIF4E in Ser209 (p-eIF4E) in brain carcinogenesis of different tumor types is well established." (PMID 36994107, 2023). "As the degradation of AR triggers the increase in eIF4E phosphorylation by Mnk1/2, combination of AR antagonists and mTOR inhibitors was effective in suppressing tumor growth." (PMID 36831540, 2023). "A study showed that eIF4E haploinsufficient mice were physiologically normal but significantly resistant to tumor formation." (PMID 37631029, 2023). "Studies have provided proof-of-concept that a translation inhibitor that reduces eIF4E phosphorylation impairs the aggressiveness of liver cancer in mice, potentially enhancing the anti-tumor immune response." (PMID 36902316, 2023). "Phosphorylated eIF4E is a convergence point for many pro-tumor pathways as well as immunoregulatory pathways." (PMID 39171279, 2023). "Most of the eIF4E-sensitive mRNAs have a long and highly structured 5’UTR region, and these mRNAs encode many proteins associated with cell proliferation and tumor progression, including MYC, VEGF, cyclin, and others." (PMID 36830614, 2023). "We further validated the effect of eIF4E on tumor progression and the relationship between eIF4E and markers of VM formation through in vivo animal experiments." (PMID 37217473, 2023). "Compared with its effect on the control group, IKE-mediated tumor suppression was weakened in the EIF4E-knockdown group, but enhanced in the ALDH1B1-knockdown group." (PMID 36274088, 2022). "In tumor tissues, EIF4E and NCBP2 were highly expressed, while WDR4 and NCBP1 were moderately expressed." (PMID 35784919, 2022). "It is reported that ribavirin can compete with the m7G cap to bind eIF4E, reduce the translation ability of the eIF4E complex, and reduce tumor proteins such as Mcl-1, to play an antitumor role." (PMID 35677157, 2022). "4E-BP1 suppresses eIF4E expression, and the overexpression of 4E-BP1 will make tumor cells sensitive to rapamycin as eIF4E plays a critical role in controlling translation 87 and tumor progression." (PMID 36313041, 2022). "Given that MNKs knock out in mice did not affect the normal phenotype, and the phosphorylation of eIF4E is essential for tumor progression, development of MNK inhibitors would be an effective treatment for related diseases." (PMID 35877722, 2022). "On the one hand, 4E-BP1 inhibits eIF4E, preventing mRNA translation and proliferation and acting as a tumor suppressor." (PMID 36428613, 2022). "VNPP433-3β impedes reckless translation in PCa cells, a prerequisite to slowing down the active tumor proliferation by abating the binding of eIF4E and eIF4G to 5′ caps of mRNA." (PMID 36078112, 2022). "As a transcription factor, hnRNPK binds to the eIF4E promoter region and 3′ untranslated region of p21 mRNA, inhibiting p21 translation and increasing translation initiation, cell division, and tumor formation." (PMID 35352475, 2022). "Although upregulated EIF4E is well characterized in promoting tumor growth, we provide evidence that EIF4E has a tumor suppressor function in HT-1080 and Calu-1 cells as it binds to ALDH1B1 to induce ferroptosis." (PMID 36274088, 2022). "The eIF4E translation initiation factor has oncogenic properties and concordantly, the inhibitory eIF4E-binding protein (4EBP1) is considered a tumor suppressor." (PMID 35626002, 2022).
tumor (continued). "For one thing, 4EBP1 has the tumor suppressive activity where 4EBP1 inhibits eIF4E and, thus, blocks mRNA translation and proliferation." (PMID 36575176, 2022). "The significance of activating EIF4E-dependent ferroptosis for tumor treatment needs to be further verified in human clinical trials." (PMID 36274088, 2022). "It has been already found for the critical roles of eIF4E in tumor cell growth, proliferation and migration while inhibition of eIF4E would attenuate the malignancy of tumor cells and increase the sensitivity of RCC cells to chemotherapy and immunotherapy." (PMID 35495133, 2022). "As demonstrated in vitro, the levels of Mnk1 and its target p-eIF4E were significantly reduced in tumor tissues of the galeterone/VNPP433-3β-treated animals." (PMID 36078112, 2022). "In OC, 4EBP-based peptides can prevent cap-dependent translation by binding to the eIF4E factor, ultimately repressing tumour progression." (PMID 35062979, 2022). "For example, inhibitors of eIF4E such as 4EGI-1, 4E1RCat, and 4E2RCat have shown anti-tumor effects in preclinical trials." (PMID 36552834, 2022). "During mTOR/AKT/PI3K activation, 4E-BP1 is phosphorylated, which frees and activates eIF4E and stimulates translation and tumor growth in vivo." (PMID 35626002, 2022). "4HNE-mediated tumor suppression was reduced in the EIF4E-knockdown group, but enhanced in the ALDH1B1-knockdown group." (PMID 36274088, 2022). "The activation of S6K and eIF4E can increase the drug resistance of tumor cells to chemotherapy drugs." (PMID 34869595, 2021). "For instance, an antisense oligonucleotide against eIF4E delivered by intravenous injections prevented tumor growth by repressing the translation of oncogenic factors dependent on elF4E function." (PMID 33804958, 2021). "Alongside this, eIF4E hyperphosphorylation facilitates metastasis through epithelial‐to‐mesenchymal transition, tumor inflammation, and extracellular remodeling." (PMID 33382175, 2021). "The central initiation factor in cap-dependent translation, eIF4E, is oncogenic when overexpressed, and multiple lines of evidence support its role in tumor formation in vivo." (PMID 35048066, 2021). "Overall, these results demonstrated that the combination of CPT and imatinib decreased the tumour growth and induced cell apoptosis through eIF4E and STAT3 inhibition in vivo." (PMID 34214017, 2021). "ImmuCellAI and TIMER database were used to explore the relationship between eIF4E and tumor infiltrating immune cells." (PMID 34876062, 2021). "Although there is some controversy as to the specific mechanism, ribavirin has been reported to reduce the levels of eIF4E dependent proteins and in preclinical studies to inhibit growth of various tumor types." (PMID 34639005, 2021). "Together, these findings show that phospho-eIF4E is necessary for efficient carcinogen-induced tumor initiation." (PMID 34032633, 2021). "In pancreatic carcinoma, Mnk-mediated phosphorylation of eIF4E was responsible for translational upregulation of Sox2, which promoted tumor recurrence after radiation." (PMID 34639005, 2021). "Analysis of the tumor pathological stages indicated that eIF4E expression was higher in stage 3 and nodal metastasis N2 status, indicating that eIF4E was related to the prognosis and higher risk in patients with advanced BRCA." (PMID 34876062, 2021). "SBI-756 synergy with venetoclax in vitro was recapitulated in vivo, with the combination reducing tumour progression that correlated with prevention of eIF4E-eIF4G1 interaction." (PMID 33318657, 2021). "In cell lines, eIF4E overexpression promotes foci formation, growth in soft agar, invasion, migration, tumor formation, and apoptotic rescue from a variety of stimuli." (PMID 34944805, 2021). "Consistent with such molecular observations, increased eIF4E levels have been associated with malignant progression and poor therapeutic outcome, and in preclinical models, targeting eIF4E has been reported to inhibit tumor growth." (PMID 34639005, 2021).